CD46 (CD46 molecule)
Diseases named in the same sentence as CD46 in open-access papers (continued):
Sharing a sentence is not in itself a finding about the gene and the disease.
prostate carcinoma (13 papers, 2016 to 2025). A carcinoma that arises from epithelial cells of the prostate gland. "CD46 is highly expressed in both primary and metastatic castration-resistant prostate cancer specimens and was associated to tumor stage in renal clear cell carcinoma." (PMID 34572075, 2021). "If induced by STAT3 and IL-6, CD46 expression protects cancer cells against complement lysis and fosters a pro-tumoral profile in breast and prostate cancers." (PMID 40370471, 2025). "In this regard, various new biomarkers are being tested for PSMA-negative prostate cancer, most notable novel biomarkers being tested are CD46, human KLK3, and VE-cadherin." (PMID 38773983, 2024). "In this study we developed a YS5-based CD46-targeted 212Pb radiotherapy and studied efficacy in three prostate cancer animal models." (PMID 36906664, 2023). "A new prostate cancer cell surface target, CD46, was found and validated using the UA20 single-chain antibody fragment (scFv)." (PMID 37760506, 2023). "YS5 is also undergoing evaluation as a diagnostic immunoPET agent (NCT05245006) in a first-in-human study of 89Zr-DFO-YS5 for detection of CD46 positive malignancy in men with prostate cancer." (PMID 37760506, 2023). "CD46 is a new prostate cancer cell surface target that we identified and validated, which shows lineage independent homogeneous expression in both adenocarcinoma and small cell neuroendocrine mCRPC, differentiating from commonly targeted antigens such as PSMA." (PMID 36906664, 2023). "This tumour escape mechanism of prostate cancer cells was exploited to develop an antibody–drug conjugate able to target high positive CD46 cells and release anti-tumor agents, specifically in cancer cells." (PMID 34572075, 2021). "Basing on the evidence that the expression of CD46 is high in prostate cancer tissue and CRPC but low in normal tissues, CD46 represents an ideal target for ADC therapy." (PMID 33557050, 2021). "Nonetheless, it is interesting to observe the further results assessing the efficacy and safety profile of other prostate cancer specific antigens-based ADCs, such as sacituzumab govitecan along with CD46-based and B7-H3-based ADCs." (PMID 33557050, 2021). "For example, one study reported that 35% of patients with colon or prostate carcinoma overexpressed CD46, while in other cancers (such as brain, lymphoma and lung), ~11% of tissue samples overexpressed CD46." (PMID 33147799, 2020). "In this study, we first investigated the expression levels of CD46 in various tumors using tissue microarrays, demonstrating that CD46 overexpression was prevalent in prostate cancers (PCa) and colorectal cancers (CRC)." (PMID 27203670, 2016). "Moreover, an immunoPET probe, which targeted CD46 in vivo in several models of prostate cancer, demonstrated that the probe localized with specificity primarily to the CD46+ tumor." (PMID 40309774, 2025). "Another highly expressed mCRP by prostate cancer cells is CD46, a transmembrane glycoprotein expressed on all nucleated cells, that functions to protect excessive complement activation by acting as a cofactor in the proteolytic cleavage of C3b and C4b, mediated by Factor I." (PMID 34572075, 2021). "Accordingly, we previously developed the CD46 targeted, 225Ac labeled antibody, 225Ac-DOTA-YS5, and demonstrated its efficacy in preclinical models of prostate cancer." (PMID 38389832, 2024). "The result from this first of its kind CD46-targeted 212Pb radioimmunotherapy study demonstrates that 212Pb-TCMC-YS5 is well tolerated and efficacious against prostate cancer in both CDX and PDX models." (PMID 36906664, 2023). "The research for the best candidate for ADC therapy in prostate cancer has led to a series of studies in which STEAP, TROP2, PSMA, CD46 and B7-H3 are the main actors." (PMID 33557050, 2021).
prostate carcinoma (continued). "The CD46-ADC approach has also shown efficacy in metastatic castration-resistant prostate cancer, utilizing a tubulin inhibitor conjugated as the ADC added to a macropinocytosing anti-CD46 antibody (Ab)." (PMID 33147799, 2020). "In addition, for prostate cancers, ADCs are primarily focused on six-transmembrane epithelial antigen of prostate 1 (STEAP1), TROP2, prostate-specific membrane antigen (PSMA), CD46, and B7-H3 as the potential targets." (PMID 38933670, 2024). "As for prostate cancer, researchers are focusing on STEAP1, TROP2, PSMA, CD46 and B7-H3 as optimal antigens which may be targeted by ADCs." (PMID 33557050, 2021). "Other studies of the CD46-ADC in a prostate cancer model system also demonstrated that it potently and selectively killed prostate cancer cell lines but not normal cells." (PMID 40309774, 2025).
bladder cancer (11 papers, 2017 to 2025). "Alternatively, in bladder cancer cells, retargeting of adenovirus to CD46 was associated with increased transduction efficacy and subsequent cytotoxicity." (PMID 38037840, 2024). "Emerging findings have indicated that overexpression of CD46 in solid cancers such as breast, ovarian, colorectal, and bladder cancers may protect cancer cells from destruction caused by the complement system." (PMID 38919630, 2024). "This indicated that CD46 facilitates bladder cancer cell migration and invasion via MMP9 expression." (PMID 40309774, 2025). "In a study utilizing bladder cancer cell lines, CD46 overexpression enhanced the upregulation of MMP9 to trigger phosphorylation of p38 MAPK and PKB and to promote increased activity of activator protein 1 (AP-1) activity via c-Jun." (PMID 40309774, 2025). "In a series of studies, it was shown that targeting CD46 chimeric Ad5/35 vectors could increase antitumor activity, decrease liver toxicity, and improve the safety profile of treatment for cervical, colorectal and bladder cancers, especially low-risk bladder cancer." (PMID 38919630, 2024). "In a murine model of metastatic bladder cancer, targeted downregulation of Crry (the murine counterpart of CD46) induced a protective antitumor CD8+ T-cell response." (PMID 38919630, 2024). "Here, we studied the in vitro effects of cetuximab monoclonal antibodies (mAbs) targeting EGFR on the bladder cancer cells and role of CD46." (PMID 36575233, 2022). "Restoration of CD46 expression protected the bladder cancer cells from cetuximab-mediated inhibition of AKT and ERK phosphorylation." (PMID 36575233, 2022). "For example, exon 13 skipping in CD46 and the exon 13-containing CD46 isoform play opposite roles in bladder cancer development, and exon 13 skipping remarkably accelerated DNA synthesis, cancer cell proliferation, migration and invasion." (PMID 34722250, 2021). "Upregulation of CD46 for instance, is detected in primary and metastatic prostate cancer, as well as in bladder cancer." (PMID 32957644, 2020). "This study evaluated Ad-mediated therapeutic efficacy using either CAR-targeting Ad5 or CD46-targeting Ad5/35 fiber chimera in bladder cancer cell lines." (PMID 30201920, 2018). "The CAR expression pattern, as well as CD46 expression pattern in bladder cancer cell lines, reported here are consistent with previous reports." (PMID 30201920, 2018). "In summary, our data suggest that modifying the adenoviral fiber knob to target CD46 gave rise to a highly effective way to target bladder cancer cells in vitro and in vivo, representing a promising therapeutic approach to treat bladder cancers." (PMID 30201920, 2018). "Here, we demonstrated that in all five bladder cancer cell lines tested, Ad5/35 had a much higher transduction efficacy and cytotoxicity compared with Ad5; this likely reflects the more abundant expression of CD46 in these bladder cancer cells." (PMID 30201920, 2018). "We then performed in vitro and in vivo experiments using several human bladder cancer cell lines, demonstrating that for these cells, a CD46-targeted Ad cancer gene therapy is much more effective than a CAR-targeted therapy." (PMID 30201920, 2018). "In bladder cancer cell lines, expression levels of CD46 and CAR were highly correlated with Ad5/35- and Ad5-mediated gene transduction and cytotoxicity, respectively." (PMID 30201920, 2018). "Suppression of CD46 in all bladder cancer cells significantly decreased Ad5/35-mediated gene delivery, whereas it did not affect Ad5-mediated gene transduction." (PMID 30201920, 2018). "In this study, we first correlated the expression of both CAR and CD46 to clinic-pathological features of bladder cancers." (PMID 30201920, 2018). "In contrast, all five bladder cancer cell lines used here revealed high CD46 expression levels, including those with low CAR expression levels (J82, T24, and HT-1376 cells)." (PMID 30201920, 2018).
bladder cancer (continued). "In summary, our data indicate that use of Ad5/35 fiber chimeric gene therapy vectors re-directed to CD46 provides an effective approach to enhance viral gene transduction efficacy in CAR-deficient cancers, including a subset of bladder cancers." (PMID 30201920, 2018). "Fifty-nine bladder cancer tissue samples from patients with clinical records were evaluated for their expression of CD46 and CAR by immunohistochemistry." (PMID 30201920, 2018). "The advantage of this new chimeric virus were that it can infect bladder cancer cells mediated by CD46 molecule." (PMID 28789701, 2017). "That CD46 isoforms may differ in their attenuation or promotion of bladder cancer also has been investigated." (PMID 40309774, 2025). "CD46 and midkine expression in bladder cancer cell lines have already been confirmed." (PMID 37367056, 2023). "Furthermore, it was found that bladder cancer cells treated with cetuximab inhibited CD46 expression and subsequently enhanced both CDC and ADCC." (PMID 36575233, 2022). "Furthermore, cetuximab treatment inhibited AKT and ERK phosphorylation in the bladder cancer cells and reduced the expression of CD46 membrane-bound proteins." (PMID 36575233, 2022). "Considering that all mCRPs can directly block ADCC in the target cells, overexpression of CD46 could be a survival pathway of the bladder cancer cells to avoid innate immunity." (PMID 36575233, 2022). "In order to evaluate whether a change in CD46 expression levels affects Ad5/35-mediated gene transduction, lentiviruses were used to either overexpress CD46 or suppress endogenous CD46 in all five bladder cancer cells." (PMID 30201920, 2018). "However, because of the inverse correlation between CD46 expression and cancer malignancy in bladder cancer patients, careful consideration needs to be given to select patients for effective adenoviral cancer gene therapy." (PMID 30201920, 2018). "In addition, the overall survival of bladder cancer patients tended to correlate with CD46 expression during a follow-up study up to 72 months (p = 0.068 by the log-rank test)." (PMID 30201920, 2018). "CD46 gene expression was higher in bladder cancer cells than in HEK 293 (all p < 0.01)." (PMID 28789701, 2017). "We utilized Ad5/F11p containing the chimeric fiber gene encoding the Ad5 fiber tail domain and Ad11p fiber shaft and knob domains to construct bladder cancer-specific chimeric type viruses Ad5/F11p-PSCAE-UPII-E1A, which can infect bladder cancer cells mediated by CD46 molecule." (PMID 28789701, 2017). "We hypothesized that CD46 provides protection to the bladder cancer cells against mAb therapies." (PMID 36575233, 2022). "Overall, our findings suggest that bladder cancer cells overexpress both CAR and CD46, and that adenoviral cancer gene therapy targeting CD46 represents a more suitable therapy option than a CAR-targeting therapy, especially in patients with low risk bladder cancers." (PMID 30201920, 2018). "This study was limited to elucidating the role of CD46 in the regulation of CDC and ADCC in bladder cancer cells." (PMID 36575233, 2022). "Together, CD46 exhibited a cancer-protective effect against both direct (by involvement of PBMC or complement) and indirect cytotoxic activity by cetuximab in bladder cancer cells." (PMID 36575233, 2022). "For this, we chose the EJ bladder cancer cells as xenograft tumor, as they highly expressed both CAR and CD46." (PMID 30201920, 2018). "Compared with normal urothelia, bladder cancer tissue generally overexpressed both CAR and CD46." (PMID 30201920, 2018). "In order to prove Ad5/F11p-PSCAE-UPII-E1A enters into bladder cancer by CD46 molecules but not CAR for killing bladder cancer cells specifically, the mRNA level expression of CAR and CD46 in bladder cancer cells surface were quantified by qRT-PCR." (PMID 28789701, 2017).
lymphoma (10 papers, 2010 to 2025). A malignant (clonal) proliferation of B- lymphocytes or T- lymphocytes which involves the lymph nodes, bone marrow and/or extranodal sites. "Upon investigating SNPs linked to FL survival in previous studies, we observed a shorter time to lymphoma progression for C compared to A allele carriers at rs2466571 in CD46 on 1q32 (HR = 1.37, ptrend = 0.006), at a nominally significant level." (PMID 25294155, 2014). "In line with a previous study investigating event-free survival in FL, we found that the C allele of rs2466571 in the CD46 gene was associated with shorter time to lymphoma progression (HR = 1.37, 95% CI 1.10-1.72, p = 0.006)." (PMID 25294155, 2014). "All herein investigated lymphoma cells expressed CD46 and had a dysregulated retinoblastoma pathway, which should enable LOAd infection and replication." (PMID 33666760, 2021). "In candidate-gene analysis, an association with lymphoma progression was observed for SNPs in CD46 and IL8, previously linked with lymphoma progression (CD46) and overall survival (IL8)." (PMID 25294155, 2014). "As a means to overcome this issue, they identify a recombinant adenovirus type 35 fiber knop protein (Ad35K++) which, when incubated with lymphoma cells, leads to CD46 downregulation and cooperates with rituximab in inducing CDC." (PMID 21437222, 2010). "These authors observed that many tumors, including lymphomas, upregulate the expression of CD46, an inhibitory complement receptor." (PMID 21437222, 2010). "Downregulation of the expression of mCRPs CD46, CD55, and CD59 improved the efficacy of rituximab and the anti-CD20 mAb ofatumumab in lymphoma and leukemia cell lines and primary CLL samples." (PMID 28658265, 2017). "Firstly, we analyzed the expression levels of CD46, the cellular receptor for BVDV entry, on HMCLs, and B-ALL, T-ALL, lymphoma cell lines (defined as non-MM cells) by flow cytometry." (PMID 32653014, 2020). "Targeting of the complement regulatory function of CD46 with mutant proteins derived from adenovirus Ad35 that bind to CD46 with very high affinity enhances response to Rituximab, an anti-CD20 antibody in lymphomas in non-human primates." (PMID 28842749, 2018). "Interestingly, we show that other cell lines, as acute leukemia and lymphoma, did not respond to the oncolytic effect of BVDV, despite their CD46 expression and BVDV ability to bind these cell lines." (PMID 32653014, 2020).
melanoma (10 papers, 2013 to 2023). A malignant, usually aggressive tumor composed of atypical, neoplastic melanocytes. "In melanoma, CD46 was reported as a major receptor facilitating the internalization of melanoma exosomes by HBMEC." (PMID 37958619, 2023). "C57BL/6 mice were s.c. engrafted with tumors derived from the syngeneic murine melanoma cell line B16, expressing the human antigens CD46 and CD20 for MV entry and as a BiTE target, respectively (B16-CD20-CD46)." (PMID 33863363, 2021). "Our results indicated that F5/35‐ZD55‐IL‐24 in combination with TMZ produced additive or synergistic antitumor effect and pro‐apoptotic effect in melanoma cells highly expressed CD46." (PMID 30406970, 2018). "Our in vivo experiments showed significant growth inhibition of ectopically CD46-overexpressing A549 lung cancer and M010119 melanoma cells in xenograft mice treated with Ad5/35-tk in combination with GCV compared to parental cells." (PMID 27203670, 2016). "Ad5/35-tk in combination with GCV was similarly effective in CD46-overexpressing M010119 melanoma cells both in vitro and in vivo." (PMID 27203670, 2016). "The high expression of CD46 in melanoma cells indicated that Ad35 is a suitable gene vector." (PMID 30406970, 2018). "Therefore, the expression of CD46 on the surface of melanoma cells and HDF cell line was analyzed." (PMID 32033013, 2020). "The expression of CAR in both melanoma cell lines was lower than that in HEK293 cells (P < 0.05), while the expression of CD46 was higher in both melanoma cell lines (P < 0.05)." (PMID 30406970, 2018). "In the present study, we used the melanoma cell lines A375 and MV3, both of which have low CAR expression, but high CD46 expression." (PMID 30406970, 2018). "To identify the receptors mediating MAdV infection we generated five novel reporter viruses for MAdV-1/-2/-3 (M1, M2, M3) transducing permissive murine (m) CMT-93 cells, but not B16 mouse melanoma cells expressing mCAR, human (h) CD46 or hDSG-2." (PMID 34910784, 2021). "This unexpected observation supports preliminary experiments in melanoma where low expression of CD46 and the absence of SLAM and Nectin-4 receptors do not correlate with efficient infection by live-attenuated vaccinal MV (manuscript in preparation)." (PMID 23586034, 2013). "Importantly, long-term survivors were protected from re-challenge with parental B16 cells, indicating activation of endogenous T cells specific for B16 melanoma antigens as opposed to human CD20 or CD46 antigens." (PMID 33863363, 2021). "Interestingly, the authors also studied the expression levels of the two major adenovirus receptors CAR and CD46 in primary melanoma cells and the immunohistochemical stainings of primary cutaneous of melanoma lesions from five patients were negative for CAR and positive CD46 expression." (PMID 32370135, 2020). "The expression level of CD46 molecule ranged from 16.56% to 87.67% on the surface of melanoma cells tested, while the HDF cells did not express CD46 (0.36%)." (PMID 32033013, 2020).